CRP (C-reactive protein)
Diseases named in the same sentence as CRP in open-access papers (continued):
Sharing a sentence is not in itself a finding about the gene and the disease.
depression (continued). "Altered mental status and comorbid depression are important clinical problems associated with stroke, and some studies report a correlation between altered mental status after stroke and elevated CRP." (PMID 36769677, 2023). "In addition, 4 mtDNA variants were detected to interact with CRP for both anxiety and depression, including m.12633C>A(MT-ND5), m.9899T>C(MT-CO3), m.4561T>C(MT-ND2), m.11377G>A(MT-ND4)." (PMID 37344456, 2023). "Moreover, higher CRP showed the largest associations with appetite changes and fatigue than other depression nodes in another large community sample (Moriarity, Horn, Kautz, Haslbeck, & Alloy, 2021a)." (PMID 35924730, 2023). "In addition, loci linked to an increased risk of depression are also linked to an increased risk of coronary artery disease and elevated levels of total cholesterol, low-density lipoprotein, and c-reactive protein." (PMID 38084332, 2023). "In addition, elevated levels of CRP are associated with increased risk for development of depression in the general population." (PMID 35758834, 2022). "Loci associated with increased risk for depression were also associated with increased risk of coronary artery disease and higher total cholesterol, low-density lipoprotein and c-reactive protein levels, while there was a mixed pattern of effect direction for the other risk factors." (PMID 35560157, 2022). "A prospective cohort study investigated whether depression and apathy in the elderly subjects could be associated with CRP levels." (PMID 35163538, 2022). "We aimed to test the hypothesis that a self-report history of depression is associated with a smaller decrease in CRP levels from hospital admission to 3-month follow-up in patients with acute myocardial infarction (MI)." (PMID 35566447, 2022). "Interestingly, we detected that, after considering the effects of inflammatory mediators (TJC, CRP, and GM-CSF) in regression analyses, IL-10 was inversely associated with depression, fatigue, physio-somatic, and overall PP ratings." (PMID 35330475, 2022). "We aimed to characterize the association between lifetime smoking and depression, as well as to assess the role that genetically-predicted C-reactive protein (CRP) level, (an archetypal generalized inflammatory marker) and/or IL-6 activity, as a potential explanation for this association." (PMID 36057695, 2022). "In addition, genetic polymorphisms in inflammatory factors (e.g. IL-1β, TNF, and CRP) are strongly associated with depression and treatment outcomes." (PMID 36186850, 2022). "However, a study of midlife adults reported that depression was associated with CRP five years later only among Black participants, and four years later only among men." (PMID 35617264, 2022). "Increased CRP levels are associated with increased anxiety and depression risk." (PMID 35558424, 2022). "CRP has been found to be associated with depression in obese men only." (PMID 35360574, 2022). "Addressing a history of depression as a risk factor of persistently elevated CRP levels may also be considered to prevent the development of MI-induced PTSS." (PMID 35566447, 2022). "This study examined whether depression, anxiety, and substance use-related symptoms were associated with CRP concentrations in the blood after adjusting for relevant medical, social, and demographic covariates." (PMID 35821205, 2022). "Similarly, biomarkers were included that have been widely tested for association with depression (CRP, vitamin D) but we cannot exclude interactions with other biomarkers." (PMID 35438196, 2022). "The IVW method also identified evidence for associations of genetically-predicted depression and lifetime smoking index (ORDep-Smk = 1.09, 95% CI: 1.06–1.13, p < 0.001), and between genetically-predicted CRP levels and lifetime smoking index (ORCRP–Smk = 1.03, 95% CI: 1.02–1.05, p < 0.001)." (PMID 36057695, 2022). "Elevated levels of CRP are associated with an increased risk of depression." (PMID 36235852, 2022).
depression (continued). "Furthermore, we used a smaller (47 independent IVs), non-overlapping CRP GWAS37, which showed a similar reciprocal associations between smoking and CRP, and similar CRP and depression findings." (PMID 36057695, 2022). "For example, while Piantella and colleagues agreed with other literature that IL-6 was associated with higher depressive symptoms in women exposed to workplace stress, they observed that higher C-reactive protein levels were associated with depression only in men." (PMID 35493954, 2022). "In addition, high levels of sIL6R are associated with lower CRP production through classical signaling, which indicates a high risk of depression." (PMID 36009493, 2022). "For the six loci shared between depression and CAD (conjFDR<0.05), five (83%) of the lead SNPs had concordant direction of effect, 12 loci (86%) for TG, 6 loci (60%) for LDL, 6 loci (75%) for CRP which implies that CAD, higher TG, LDL and CRP increase the risk for depression." (PMID 35560157, 2022). "Besides, depression relates to the disorder of immune system, and the expression of inflammation markers (IL-6, C-reactive protein, TNF-α) increases the risk of DN." (PMID 36538528, 2022). "Our finding of extensive shared variants between depression and lipids and depression and CRP suggests there may be a large numbers of variants which impact both phenotypes via pleiotropic mechanisms." (PMID 35560157, 2022). "This was the first study to assess the association of DII and depression among pre-menopausal women, and the first to assess the mediation effect of inflammation, as assessed by CRP, on the association of DII and depression among both pre- and post-menopausal women." (PMID 35565951, 2022). "Moreover, the association between inflammatory markers, in particular CRP, has been linked to altered appetite symptoms of depression." (PMID 35361785, 2022). "Different biological processes including elevated inflammatory mediators (i.e., C-Reactive Protein (CRP)), tissue damage, and chronic stress response may predispose cancer patients to depression." (PMID 36421342, 2022). "Furthermore, several studies have investigated the role of SNPs in the association between CRP levels and depression with mixed results." (PMID 35163538, 2022). "Baseline high CRP levels were associated with depression symptoms severity." (PMID 35163538, 2022). "In other words, persistently higher CRP risk-categories and log CRP levels may explain the previously reported link of premorbid depression and poorer prognosis of patients with CHD." (PMID 35566447, 2022). "For depression, the association with several inflammatory biomarkers, including CRP, could explain elevated mortality risks from natural causes (rather than external ones), although the etiological mechanisms for these associations are unclear." (PMID 35085232, 2022). "Similarly, in a study of older adults, depression six years earlier was associated with levels of interleukin-6 (IL-6) and (marginally) CRP." (PMID 35617264, 2022). "Similarly, a cross-sectional study studied the association between variants in the CRP gene that influence protein levels and depression in 990 people aged ≥65 years whose psychopathology was assessed through MINI and CESD." (PMID 35163538, 2022). "For example, CRP is a marker of inflammation and predicts depression and cardiovascular risk." (PMID 36358455, 2022). "In regression analyses, evidence for association of CRP with depression symptoms remained after adjusting for anxiety symptoms (OR=1·06; 95% CI, 1·05–1·08), but the association of CRP with anxiety symptoms switched its valence after adjusting for depressive symptoms (OR=0·98; 95% CI, 0·97–0·99)." (PMID 34505025, 2021). "A significant association was noted between depression and CRP." (PMID 33672126, 2021).
depression (continued). "In particular, levels of IL-6 and CRP have been associated with an increased likelihood of experiencing treatment-resistant depression, suggesting that there is a role for anti-inflammatory interventions to be used as adjunctive treatments for patients with MDD." (PMID 33652997, 2021). "Tests for inflammation, including simple blood tests such as CRP, can be used and may help serve as a marker of the biological risk for depression." (PMID 35444703, 2021). "These diseases extend from obesity to so-called “MS,” which leads to the activation of some inflammatory factors, cytokines and chemokines, such as interleukin-6 (IL-6) and C-reactive protein, which are significantly associated with MS and the severity of depression." (PMID 34531719, 2021). "Importantly, a similar signature of inflammatory changes, including elevated blood levels of interleukin (IL)-6, tumor necrosis factor (TNF)-α, and CRP, was also found in inflammation-associated depression." (PMID 32873895, 2021). "Increased CRP levels have also been shown to be associated with more severe symptoms of depression." (PMID 33517931, 2021). "CRP was more strongly associated with depression in women than in men." (PMID 34505025, 2021). "Univariate logistic regression analysis showed postoperative depression at 1 year was associated with age, allergy status, a higher preoperative hs-CRP level (>2.02 mg/L), and preoperative subjective measurements (ENS6Q, SNOT-25, BDI-II, and BAI scores) (all p < 0.001)." (PMID 34943627, 2021). "•Elevated CRP (≥3mg/L) was associated with both somatic and psychological symptoms of depression." (PMID 34729541, 2021). "Evidence suggests that elevated CRP levels in depressed patients are associated with higher depression severity and somatic symptoms (e.g., fatigue, changes in appetite, and sleep), rather than psychological symptoms (e.g., hopelessness, excessive/inappropriate guilt)." (PMID 34729541, 2021). "Higher levels of CRP are associated with increased depression severity." (PMID 35096747, 2021). "Mechanistically, the observed increased depression risk conferred by IL6R SNPs that increase CRP levels could happen as a result of either increased IL-6 classic or trans-signalling." (PMID 34505025, 2021). "•First study of both serum and DNAm CRP associations with depression/neuroimaging." (PMID 33221487, 2021). "It is still unclear whether and to what extent elevated CRP levels are associated with psychological distress and depression in the general population." (PMID 34680097, 2021). "While we found a similar direction of effect of the minor allele on risks for schizophrenia and depression, the evidence was weaker in depression in univariable MR analysis, and may have been masked by genetic associations with CRP." (PMID 34280516, 2021). "In the adjusted model all serum CRP quintiles were significantly associated with a higher pairs matching z-score whilst BD-I, recurrent major depression (severe), and recurrent major depression (moderate) all remained significantly associated with a lower pairs matching z-score." (PMID 33517931, 2021). "We have examined specificity of association by testing whether the association of CRP with depression and anxiety is stronger for one outcome than the other, or is similar between outcomes." (PMID 34505025, 2021). "Within our sample, lifestyle factors (i.e., smoking, inactivity, and alcohol consumption) had the largest impact on the association between inflammation and depression during the pandemic, but even when these and other factors were taken into account, the relationship for CRP remained significant." (PMID 34887380, 2021). "Using population-based data from up to 144,890 UK Biobank cohort participants, we tested associations of circulating CRP concentrations with depression and anxiety symptom scores and probable diagnosis, including tests for linearity, disorder-specificity and sex difference." (PMID 34505025, 2021).
depression (continued). "Data supporting the role of inflammation in depression are extensive: depression is associated with increased inflammatory biomarkers like elevated CRP and Interleukin 6 (IL-6), and a pro-inflammatory state might worsen the outcome of depression." (PMID 33801190, 2021). "Conversely, PRS for immune-metabolic traits such as body mass index (BMI) and C-reactive protein are strongly associated with the atypical depression, and patients with the atypical subtype were found to carry more genetic risk variants for BMI and C-reactive protein." (PMID 32568380, 2020). "Certain risk factors for CHD, specifically IL-6, CRP and triglycerides, are likely to be causally linked with depression, so these could be targets for treatment and prevention of the illness." (PMID 30886334, 2020). "Moreover genome-wide association stud (GWAS) analysis showed that various proinflammatory cytokines including IL-1β, TNF, and CRP have been linked to depression and response to treatment." (PMID 32380663, 2020). "In addition, Mendelian randomization studies support potential causal associations between IL-6, CRP and depression." (PMID 32755646, 2020). "As individuals prenatally exposed to alcohol are at higher risk of experiencing adverse environments during early postnatal life and mental health problems including depression, this association and involvement of CRP merits further investigation in longitudinal studies." (PMID 31992316, 2020). "IL-6, CRP and triglycerides are likely to be causally linked with depression, so could be targets for treatment and prevention of depression." (PMID 30886334, 2020). "In summary, using repeated measurements of CRP from childhood to young-adulthood, we report that an increasing pattern of inflammation from adolescence to early-adulthood is associated with risk of moderate/severe depression in early-adulthood." (PMID 31707310, 2020). "Secondary outcomes include assessment of mood (Calgary Depression Scale), general function (Global Assessment of Functioning), cardiovascular risk (body mass index, waist circumference, C-reactive protein, cholesterol and HbA1c) and vitamin D levels at the 6-month follow-up." (PMID 31907006, 2020). "Further investigation is needed to understand this discrepancy, which could be linked to divergent effects of IL-6 classical and trans signalling on depression risk, and/or CRP-dependent vs CRP-independent effects of IL-6 on depression risk." (PMID 30886334, 2020). "BMI (OR = 1.13; 95 % C.I., 1.05−1.22), HOMA2 (OR = 1.12; 95 % C.I., 1.01−1.26), triglycerides (OR = 2.09; 95 % C.I., 1.35−3.24) and fasting insulin (OR = 1.42; 95 % C.I., 1.01-2.12) were associated with current depression with raised CRP, after adjusting for potential confounders." (PMID 32339985, 2020). "We hypothesised that persistently high or increasing levels of CRP from childhood through to early-adulthood would be associated with the risk of depression in early-adulthood assessed at age 18 years." (PMID 31707310, 2020). "In addition, childhood adversity/maltreatment and adult depression, both alone and in combination, are also associated with elevations in CRP." (PMID 31992316, 2020). "Higher levels of C-reactive protein are associated with risk for the development of de novo depression, suggesting that inflammation contributes at least in part to the genesis and progression of depression." (PMID 31948461, 2020). "Similarly, another study examined the association between the severity of depression and serum CRP levels." (PMID 30899619, 2019). "In our results, hs-CRP was considerably associated with depression in men after adjusting BMI." (PMID 30760746, 2019). "Moreover, elevated CRP and IL-6 were found significantly more frequently in individuals with rMDD than in healthy controls, and depression was associated with higher CRP levels, especially in the case of cumulative episodes of depression." (PMID 30995920, 2019).
depression (continued). "Such confounding factors could have contributed to the inconsistent association between hs-CRP and depression." (PMID 30760746, 2019). "Several minerals and vitamins (e.g., magnesium, zinc, selenium) present in fruits and vegetables may reduce plasma concentrations of C-reactive protein, a marker of low-grade inflammation associated with depression." (PMID 31690283, 2019). "Furthermore, studies found that higher cytokine and C-reactive protein (CRP) levels in childhood increased the risk to develop depression and schizophrenia." (PMID 31214060, 2019). "Depression (p = 0.045), triglycerides (p = < 0.001) and hs-CRP (p = 0.021) were negatively associated with HDL-cholesterol levels, whereas female sex (p < 0.001), age (p = 0.005) and total cholesterol (p < 0.001) were positively associated with HDL-cholesterol levels in 171 patients." (PMID 30885233, 2019). "Moreover, the association between hs-CRP and depression in multiple linear regression analysis remained significant in men only." (PMID 30760746, 2019). "Lastly, the lack of information on medications, particularly psychotropics, could attenuate the real association between hs-CRP and depression and might affect the results." (PMID 30760746, 2019). "In an epidemiological study, CRP was associated with depression only in obese men16." (PMID 30760746, 2019). "This difference among studies might confound the effect of BMI on the association between hs-CRP and depression." (PMID 30760746, 2019). "For example in UK Biobank, associations between CRP and cognition, and any interactions with diagnoses (depression, inflammatory conditions) could be examined." (PMID 31158611, 2019). "Similarly, higher baseline CRP and IL-6 levels are not only associated with cognitive symptoms of depression but also predict cognitive symptoms at an average follow-up of 11.8 years, suggesting that inflammation precedes the progression of MDD." (PMID 30995920, 2019). "In addition to the association with depression severity and risk of inpatient hospitalization, high levels of CRP have also been associated with greater likelihood of completed suicide." (PMID 29329256, 2018). "Using brain-wide, CRP-Glu ReHo contrast maps, a covariance network of 41 regions-of-interest (ROIs) with similar ReHo decreases was identified in the High CRP-Glu group and was located to brain structures previously implicated in depression." (PMID 30202011, 2018). "High-risk levels of c-reactive protein were significantly associated with increased odds of depression among white women (adjusted odds ratio (aOR) = 1.7, 95% CI: 1.1–2.5) and men (aOR = 1.8, 95% CI: 1.1–2.8) but not black women (aOR = 0.8, 95% CI: 0.6–1.1) or men (aOR = 0.9, 95% CI: 0.5–1.5)." (PMID 30154326, 2018). "Based on findings from previous studies, we hypothesized that Asp358Ala would be associated with elevated serum IL-6 but decreased serum CRP levels at age 9 years, and with decreased risks of depression and psychosis at age 18 years in the ALSPAC birth cohort." (PMID 29197507, 2018). "In response to these results, Dantzer postulated that the inflammatory status underlying elevated CRP levels at an early age could also influence the development or recurrence of depressive disorders in later life." (PMID 30460320, 2018). "However, higher depression scores were positively associated with CRP levels among individuals with the A–G–T haplotype." (PMID 27555379, 2017). "Elevated levels of inflammatory markers such as C-reactive protein (CRP) may increase the risk of a first episode of depression." (PMID 28760142, 2017). "To date, how BMI alters the etiological factors involved in the CRP-depression association remains unknown, and studies related to this topic across entire BMI ranges (from underweight to obese) are scarce." (PMID 28128231, 2017).